TRIM8 (tripartite motif containing 8)
Diseases named in the same sentence as TRIM8 in open-access papers (continued):
Sharing a sentence is not in itself a finding about the gene and the disease.
breast cancer (7 papers, 2021 to 2024). A primary or metastatic malignant neoplasm involving the breast. "First, we found that TRIM8 gene copy numbers were inversely associated with the infiltration levels in breast cancer, including B cell, CD4+Tcell, and macrophage." (PMID 35368651, 2022). "Our findings uncovered the potential role of TRIM8 in breast cancer and would move us closer to understand the underlying mechanisms between TRIM8 and tumor-immune." (PMID 35368651, 2022). "First, we downloaded data from TCGA (The cancer genome atlas), GEO (Gene expression omnibus) database and METABRIC (Molecular Taxonomy of Breast Cancer International Consortium) to evaluate the association between TRIM8 expression and the survival of breast cancer." (PMID 35368651, 2022). "Significant association was found between TRIM8 expression and immunoinhibitors in breast cancer." (PMID 35368651, 2022). "Moreover, there was a significant association between TRIM8 expression and abundance of 20 TILs in breast cancer." (PMID 35368651, 2022). "Moreover, in breast cancer, downregulated TRIM8 was associated with a poor prognosis." (PMID 35565438, 2022). "Recently, TRIM8 was found downregulated in Breast Cancer (BC) and this is associated with poor prognosis." (PMID 33807506, 2021). "In this study, we first determined the expression and prognostic value of TRIM8 in patients with breast cancer." (PMID 35368651, 2022). "We then mapped a scatter plot using TCGA dataset which indicated that TRIM8 was significantly lower in breast cancer as compared with normal tissues." (PMID 35368651, 2022). "To explore the correlation between TRIM8 expression and prognosis of breast cancer patients, we performed survival analysis using the TCGA database." (PMID 35368651, 2022). "Studies have shown that TRIM8 overexpression inhibits the proliferation and invasion of laryngeal squamous cell carcinoma and breast cancer." (PMID 36353542, 2022). "The expression level of TRIM8 was lower in breast cancer tissues than in normal tissues, and high TRIM8 expression levels were strongly correlated with better OS, PFS and RFS in the breast cancer population." (PMID 35368651, 2022). "We further evaluated the expression of TRIM8 in different molecular subtype patients with breast cancer in TCGA cohort." (PMID 35368651, 2022). "Representative IHC image showed that TRIM8 staining was higher in breast cancer than in normal tissues." (PMID 35368651, 2022). "The positive role of TRIM8 expression prognosis of patients with breast cancer was in accordance with different potential functional roles of immune cell types." (PMID 35368651, 2022). "In conclusion, our results suggest that TRIM8 was expressed at low levels in breast cancer tissues, and high expression of TRIM8 in breast cancer patients predicted better prognosis." (PMID 35368651, 2022). "Survival curves were estimated by the Kaplan-Meier analysis which suggested that patients with high TRIM8 expression significantly correlated to longer OS in breast cancer patients (p < 0.05)." (PMID 35368651, 2022). "The results showed that high TRIM8 expression levels were strongly correlated with longer OS in the breast cancer population (pooled HR = 0.87, 95% CI, 0.78–0.97)." (PMID 35368651, 2022). "TRIM8 also mediates the proliferation and migration ability of the cells through the NF-kB pathway, and the knockdown of TRIM8 in the breast cancer MCF7 cell line significantly reduces the cell proliferation and clonogenicity of cells." (PMID 35565438, 2022). "Previous research has demonstrated that TRIM8 expression level is closely related with immunity in breast cancer." (PMID 35368651, 2022). "There were strong correlations between TRIM8 copy numbers and immune cell infiltration, such as macrophage in breast cancer, CD4+ T Cell, and Macrophage in luminal-type breast cancer." (PMID 35368651, 2022).
breast cancer (continued). "To better understand the underlying biological function of TRIM8 gene, we conducted TISIDB analysis to determine the correlation between TRIM8 and immunomodulator in breast cancer." (PMID 35368651, 2022). "Specifically, this analysis indicated that TRIM8 expression was higher in leukemia and prostate cancer, but was lower in breast cancer, esophageal cancer, lung cancer, melanoma, and sarcoma." (PMID 35368651, 2022). "Therefore, TRIM8 was predicted to be a probable candidate as both a prognostic biomarker and a new immunotherapeutic strategy for breast cancer treatment." (PMID 35368651, 2022). "Our findings indicated that TRIM8 might be a potential link between progression and prognosis survival of breast cancer." (PMID 35368651, 2022). "The role of TRIM8 in breast cancer has rarely been reported." (PMID 35368651, 2022). "In this study, high expression of TRIM8 indicated a good prognosis in breast cancer." (PMID 35368651, 2022). "Lower TRIM8 expression was related with worse prognosis in breast cancer." (PMID 35368651, 2022). "In this study, we uncovered the immune implication and prognostic impact of TRIM8 in breast cancer." (PMID 35368651, 2022). "Furthermore, we also evaluated TRIM8 expression in 224 paired breast cancer tissues in TCGA dataset." (PMID 35368651, 2022). "TRIM8 expression was dramatically lower in breast cancer tissues in comparison with normal tissues." (PMID 35368651, 2022). "TRIM8 inhibits breast cancer proliferation through the regulation of estrogen signaling." (PMID 35565438, 2022). "Our results revealed that there is a close linkage between TRIM8 and the immunity of breast cancer." (PMID 35368651, 2022). "Altogether, these findings suggest TRIM8 may serve as a tumor suppressor gene and a putative prognostic biomarker for breast cancer." (PMID 35368651, 2022). "Moreover, knockdown of TRIM8 can significantly enhance breast cancer cell proliferation and migration both in vitro and in vivo." (PMID 33673719, 2021). "miR-665 targets TRIM8 to regulate the Wnt5a/β-Catenin and Caspase-3 signaling pathways in lung squamous carcinoma to promote cell proliferation and inhibit apoptosis; miR-665 is associated with poor prognosis and promotes metastasis by targeting NR4A3 in breast cancer." (PMID 38097567, 2023). "However, it is still unknown the relationship between TRIM8 and immune characteristics in breast cancer." (PMID 35368651, 2022). "TRIM8 might positively regulate the expression of PVRL2 in breast cancer." (PMID 35368651, 2022). "The results demonstrated that TRIM8 expression correlated well with parts of immunostimulators and MHC molecule in breast cancer." (PMID 35368651, 2022). "Among 12 breast cancer tissues examined, all of the cases were negative by immunohistochemistry for TRIM8." (PMID 35368651, 2022). "Taken together, these findings suggested TRIM8 expression in breast cancer samples is lower compared to normal samples." (PMID 35368651, 2022).
clear cell Renal Cell Carcinoma (7 papers, 2014 to 2022). "In clear cell Renal Cell Carcinoma (ccRCC), the miR-17-5p and miR-106b-5p targeted TRIM8 mRNA promoting its degradation." (PMID 33807506, 2021). "For example the rescue of TRIM8 protein levels in the aggressive and chemo-resistant clear cell Renal Cell Carcinoma by anti-miR-17, makes these cells sensitive to chemotherapy drugs like cisplatin, nutlin, sorafenib and axitinib." (PMID 30974870, 2019). "Moreover, TRIM8 was found downregulated in patients affected by chemoresistant clear cell Renal Cell Carcinoma (ccRCC)." (PMID 33807506, 2021). "The mechanisms that regulate TRIM8, especially in cancers like clear cell Renal Cell Carcinoma (ccRCC) and colorectal cancer (CRC) where it is low expressed, are still unknown." (PMID 28327152, 2017). "Thus we measured TRIM8 expression levels in patients affected by clear cell Renal Cell Carcinoma (ccRCC) or renal oncocytoma (RO)." (PMID 25277184, 2014). "Interestingly, TRIM8 down-regulation has been observed in a wide range of chemo- and radio-therapy resistant neoplasms, as in glioma, in anaplastic thyroid cancer (ATC) and in clear cell Renal Cell Carcinoma (ccRCC)." (PMID 30974870, 2019).
Ewing sarcoma (7 papers, 2023 to 2025). A small round cell tumor that lacks morphologic, immunohistochemical, and electron microscopic evidence of neuroectodermal differentiation. "Loss of TRIM8 induces EWS-FLI1-mediated overdose in Ewing sarcoma cells, leading to upregulation of apoptosis." (PMID 37875551, 2023). "Seong et al69 reported a significantly increased expression of TRIM8 (tripartite motif containing 8) in both Ewing sarcoma cells and patient samples, which demonstrated a positive correlation with the proliferative capacity of the tumor cells." (PMID 40584293, 2025). "Intriguingly, TRIM8 plays an opposite role in another bone sarcoma, namely, Ewing sarcoma, but the reason for this difference still needs further investigation." (PMID 38879525, 2024). "Next, we transfected these uAbs into A673 Ewing sarcoma cells, and successfully identified two candidates, TRIM8_SnP_5 and TRIM8_SnP_6, that degraded endogenous TRIM8 with statistical significance." (PMID 37875551, 2023). "TRIM8-targeting uAbs, specifically, induced apoptosis in Ewing sarcoma cells, in line with previous genetic studies." (PMID 37875551, 2023). "We next turned our focus to TRIM8, an E3 ubiquitin ligase itself that regulates the levels of the core fusion oncoprotein driving Ewing sarcoma, EWS-FLI111." (PMID 37875551, 2023). "This research, for the first time, identified TRIM8 as a regulator of EWSR1-FLI1, facilitating the survival of Ewing sarcoma cells by enhancing the stability and transcriptional activity of EWSR1-FLI1." (PMID 40584293, 2025). "The study demonstrated that the knockdown of TRIM8 via the CRISPR/Cas9 gene editing technique significantly diminished the proliferative capacity and augmented apoptosis in Ewing sarcoma cells." (PMID 40584293, 2025). "TRIM8 also ubiquitinates and degrades EWS/FLI, a driver fusion-TF in Ewing sarcoma." (PMID 41184227, 2025).
renal cell carcinoma (7 papers, 2014 to 2025). "We cannot definitely assert that TRIM8 deficit in Renal Cell Carcinoma is specifically due to the loss of TRIM8 heterozygosity, as other additional mechanisms, such as epigenetic silencing, could be involved." (PMID 25277184, 2014). "Prior research has supported TRIM8’s significance in IFN-γ hyper-responsiveness by connecting its deregulation to renal cell cancer and macrophage activation in systemic juvenile idiopathic arthritis." (PMID 41194165, 2025). "In cell Renal Cell Carcinoma miR-17-5p, miR-106b-5p and miR-182 bind TRIM8 mRNA leading to its degradation." (PMID 35565438, 2022). "TRIM8 overexpression blocks cell proliferation of clear cell Renal Cell Carcinoma." (PMID 33858426, 2021). "In contrast, TRIM8 inhibits renal cell carcinoma formation in vitro, suggesting that TRIM8 might also act as a tumor suppressor in some settings and may be context dependent in its function." (PMID 28100038, 2017).
Epileptic encephalopathy (5 papers, 2015 to 2025). A condition in which epileptiform abnormalities are believed to contribute to the progressive disturbance in cerebral function. "A recent study showed a lack of TRIM8 protein expression, with suppressor of cytokine signaling 1 (SOCS1) overexpression, in podocytes and tubules from a patient with a TRIM8 variant, who presented with epileptic encephalopathy and focal segmental glomerulosclerosis (FSGS)." (PMID 34930159, 2021). "TRIM8 knockdown thereby reduces excitatory synaptic transmission, perhaps giving context to studies showing that TRIM8 truncation mutants can result in early-onset epileptic encephalopathy, a neurodevelopmental disorder characterized by seizures and limited use of language." (PMID 38115822, 2023). "Heterozygous truncating variants in the Tripartite motif containing 8 (TRIM8) gene have been reported to cause epileptic encephalopathy, both with and without proteinuria." (PMID 34930159, 2021).
cardiac hypertrophy (4 papers, 2019 to 2022). "It has also been found that TRIM8 expression in the heart was greatly upregulated in cardiomyoblast H9c2 cells after stimulation with Hypoxia/Reoxygenation (H/R), overstating cardiac hypertrophy." (PMID 33807506, 2021). "TRIM8 contributed to pathological cardiac hypertrophy by prompting the activation of transforming growth factor β‐activated kinase 1‐dependent signalling." (PMID 32343488, 2020). "Genes associate with cardiac hypertrophy included JMJD1C, ANXA7, TRIM8, NGB, and AKAP13." (PMID 36071494, 2022). "In response to pressure overload (hypertrophic stimuli), TRIM8 translocates from the nucleus to the cytoplasm, promoting TAK1 ubiquitination and phosphorylation of IKK with subsequent cardiac hypertrophy triggered by aortic banding." (PMID 33807506, 2021).
Hepatic steatosis (4 papers, 2021 to 2025). Steatosis is a term used to denote lipid accumulation within hepatocytes. "Hepatocyte-specific TRIM8 overexpression causes IR, hepatic steatosis, inflammation, and fibrosis, all of which dramatically deteriorate." (PMID 40292292, 2025). "The overexpression of TRIM8 leads to insulin resistance, hepatic steatosis, inflammation, and fibrosis." (PMID 39199424, 2024). "Consistently, TRIM8 knockdown attenuates liver steatosis by reducing the secretion of pro-inflammatory modulators, such as IL-6, IL-1β, TNF-α and CXCL-2 with consequent inactivation of the NF-κB pathway." (PMID 33807506, 2021). "In the liver, TRIM8 also enhances the K63-linked ubiquitination of TAK1, thus aggravating various hepatic pathophysiological process, including hepatic ischemia /reperfusion injury, hepatic steatosis and fibrosis." (PMID 38879600, 2024). "TRIM8 and TRIM24 have been proven to enhance gene expression that promotes fibrosis in fatty liver mice models." (PMID 39199424, 2024). "The researchers found that TRIM8 was progressively elevated in liver tissue from patients without hepatic steatosis, patients with hepatic steatosis, and patients with NASH." (PMID 40292292, 2025). "In non-alcoholic steatohepatitis, TRIM8 ubiquitinates TAK1 inducing the phosphorylation and the activation of downstream c-Jun N-terminal kinase/p38/NF-κB pathways and promoting insulin resistance, hepatic steatosis and fibrosis in mouse livers." (PMID 33807506, 2021).
colorectal cancer (3 papers, 2017 to 2024). A primary or metastatic malignant neoplasm that affects the colon or rectum. "By restoring normal TRIM8 levels, CRC cells recover sensitivity to chemotherapy treatments such as Sorafenib, Axitinib, which are among the Tyrosine Kinase inhibitors currently in use for treatment of both renal and colorectal carcinoma, and also to Nutlin-3 and Cisplatin." (PMID 33673719, 2021).
developmental delay (3 papers, 2021 to 2024). "TRIM8-related neuro-renal syndrome (NRS), caused by pathogenic variants of the TRIM8 gene, is characterized by epilepsy, developmental delay (DD) and renal disorders." (PMID 39416667, 2024).
epilepsy (3 papers, 2024 to 2025). A brain disorder characterized by episodes of abnormally increased neuronal discharge resulting in transient episodes of sensory or motor neurological dysfunction, or psychic dysfunction. "Additionally, some genes (TPRKB, PRAG1, SLC25A12, and TRIM8) have been identified as associated with epilepsy, a neurological disorder characterized by recurrent seizures, that shares similar genetic vulnerability with SZ." (PMID 40282399, 2025). "TRIM8 gene mutation should be cautioned in children with epilepsy, DD, and proteinuria." (PMID 39416667, 2024). "TRIM8 gene sequencing should be considered in individuals with early onset of FSGS, particularly accompanied by symptoms of cortical dysfunction, such as epilepsy and intellectual disability." (PMID 38674071, 2024).
gastric cancer (3 papers, 2012 to 2025). A primary or metastatic malignant neoplasm involving the stomach. "However, the oncogenic function and underlying mechanism of TRIM8 in gastric cancer and glycolysis-mediated angiogenesis remain inconclusive." (PMID 41184227, 2025). "This hypothesis is further supported by the loss of expression of PIAS3, the target of TRIM8, in many tumors including human gastric carcinoma and glioblastoma multiforme tumors." (PMID 23152791, 2012). "In this study, we demonstrated that TRIM8 regulates gastric cancer cell glycolysis by mediating PGK1 K63 ubiquitination." (PMID 41184227, 2025). "Our findings highlight the pro-angiogenic role of TRIM8 in gastric cancer through K63 ubiquitination regulated-glycolysis and providing a potential strategy to eliminate gastric cancer angiogenesis by targeting TRIM8 -dependent PGK1 K63 ubiquitination." (PMID 41184227, 2025). "TRIM8 levels are positively correlated with tumor angiogenesis and poor prognosis in gastric cancer patients." (PMID 41184227, 2025). "In the present study, we investigate the role of TRIM8 in metabolism-promoted tumor angiogenesis and reveal a novel mechanism by which TRIM8 reprograms tumor cell glycolysis to promote tumor angiogenesis in gastric cancer." (PMID 41184227, 2025). "In summary, our findings elucidate a novel mechanism underlying the upregulation of angiogenesis mediated by K63 ubiquitination-regulated glycolysis in tumor cells and provide a molecular basis for eliminating gastric cancer angiogenesis by targeting TRIM8-dependent PGK1 K63 ubiquitination." (PMID 41184227, 2025). "We showed that TRIM8 and its induced K63 ubiquitination resulted in PGK1-dependent glycolysis and lactate accumulation in gastric cancer cells, which ultimately promoted tumor angiogenesis." (PMID 41184227, 2025). "In addition, we showed that K63 ubiquitination was required for PGK1-induced glycolysis and angiogenesis in gastric cancer cells expressing TRIM8, further supporting the essential role of TRIM8-mediated PGK1 K63 ubiquitination in the metabolism and angiogenesis of gastric cancer." (PMID 41184227, 2025).
Intellectual disability (3 papers, 2021 to 2024). "Lastly, we describe how TRIM8 dysfunctions are linked to inflammatory processes, autoimmune disorders, rare developmental and cardiovascular diseases, ischemia, intellectual disability and cancer." (PMID 33807506, 2021). "Mutations in the TRIM8 gene have been associated with several rare disorders including developmental delay and intellectual disability with different degrees of severity (absent or minimal speech, delayed walking or non-ambulant and intractable epileptic seizures)." (PMID 33807506, 2021).